ICAM5 (intercellular adhesion molecule 5)
Diseases named in the same sentence as ICAM5 in open-access papers:
ICAM5 is named in the same sentence as 43 diseases in open-access papers, as found by Europe PMC text mining. Sharing a sentence is not in itself a finding about the gene and the disease. The quoted sentences say what the papers report.
COVID-19 (4 papers, 2022 to 2025). A disease caused by infection with severe acute respiratory syndrome coronavirus 2. "The genetically-predicted protein levels of OAS1 (OR=0.440, 95%CI=0.315 to 0.615, P = 1.57 × 10−6), FCRL3 (OR=1.032, 95%CI=1.030 to 1.034, P = 2.40 × 10−191) and ICAM5 (OR=0.780, 95%CI=0.691 to 0.880, P = 5.74 × 10−6) showed MR association with COVID-19 severity using data from GENOMICC." (PMID 35772218, 2022). "Partly consistent with a previous MR study showing sICAM-2 lowers the risk of severe COVID-19 and in line with another MR study showing ICAM5 lowers the risk of severe COVID-19, we found ICAM-2 and ICAM-5 lower the risk of COVID-19 hospitalization." (PMID 38575325, 2024). "Two genes, ICAM1 and ICAM5, belonging to the intercellular adhesion molecule family, showed effects on COVID-19 severity in our study." (PMID 35772218, 2022). "MR and colocalization prioritized four protein targets, FCRL3, ICAM5, ENTPD5 and OAS1 that showed effect on COVID-19 severity in European ancestry." (PMID 35772218, 2022). "In addition, our study identified four additional protein targets, FCRL3, ICAM5, ENTPD5 and OAS1, that showed effect on COVID-19 severity in Europeans." (PMID 35772218, 2022).
Cognitive impairment (3 papers, 2017 to 2020). Abnormal cognition is characterized by deficits in thinking, reasoning, or remembering. "In the FXS mouse model, ICAM5 expression is aberrantly increased, correlated with the developmental delay of spine maturation and the concomitant cognitive impairment, and the reduction of ICAM5 expression rescues the behavioral disorders in Fmr1 KO mice." (PMID 31882402, 2020). "In several cases, development of cognitive disorder was accompanied by elevated levels of ICAM5 in CSF and plasma." (PMID 28580181, 2017). "To investigate the relationship between cognitive impairment and ICAM5 in HIV patients, we compared soluble ICAM5 levels in paired CSF and plasma specimens from HIV-infected individuals with or without neurocognitive impairment." (PMID 28580181, 2017). "ICAM5 could be a therapeutic target for treating cognitive impairment in FXS." (PMID 31882402, 2020). "Our results indicate a critical role of ICAM5 in spine maturation and cognitive impairment in FXS and suggest that ICAM5 is a potential molecular target for the development of medication against FXS." (PMID 31882402, 2020). "As an important regulator of spine maturation, intercellular adhesion molecule 5 (ICAM5) mRNA may be one of the targets of FMRP and involved in cognitive impairment in FXS." (PMID 31882402, 2020). "Genetic ICAM5 intervention attenuated behavioral deficits in Fmr1 KO mice, which may provide therapeutic benefits in the treatment of FXS cognitive impairment and other NDDs." (PMID 31882402, 2020). "Thus, the overexpression of ICAM5 in postnatal development in Fmr1 KO mice may be a neurobiological mechanism for FXS pathological phenotypes and a therapeutic target for the treatment of FXS cognitive impairment." (PMID 31882402, 2020).
encephalitis (3 papers, 2012 to 2019). An acute inflammatory process affecting the brain parenchyma. "The intercellular adhesion molecule-5 is solubilized under several pathological conditions, such as encephalitis, and soluble ICAM-5 is found in the serum of patients." (PMID 29311819, 2017). "In conditions of brain ischemia, epilepsy, and encephalitis, the soluble form of ICAM-5/sICAM-5 has been detected in physiologic fluids." (PMID 22312318, 2012). "Soluble ICAM-5 was detected in experimental hypoxic-ischemic injury of the brain and encephalitis." (PMID 22312318, 2012). "For example, we identify an association between the Icam5 (MGI:109430, ENTREZ:7087) gene and Encephalitis (HP:0002383) based on our method, while there are no phenotypes associated with Icam5 in the HPO database." (PMID 30809638, 2019).
fragile X syndrome (3 papers, 2019 to 2024). A genetic syndrome caused by mutations in the FMR1 gene which is responsible for the expression of the fragile X mental retardation 1 protein. "SIGNIFICANCE STATEMENT Fragile X syndrome (FXS) is characterized by dendritic spine dysgenesis and cognitive dysfunctions, while one of the FMRP latent targets, ICAM5, is well established for contributing both spine maturation and learning performance." (PMID 31882402, 2020).
bladder cancer (2 papers, 2022 to 2026). "According to RNA-Seq analyses and Western blotting experiments, the expression of c-Myc, SLC25A19, and ICAM5 was modified as a result of UCHL5 activating AKT/mTOR signaling in bladder cancer cells." (PMID 36428630, 2022). "All things considered, our findings show that increased UCHL5 expression stimulates AKT/mTOR signaling, subsequently triggering the expression of c-Myc, SLC25A19, and ICAM5, which in turn promotes carcinogenesis in bladder cancer." (PMID 36428630, 2022). "In addition to discovering that the AKT/mTOR pathway is involved in regulating the progression of bladder cancer, we also identified downstream target proteins (c-Myc, SLC25A19, and ICAM5) of UCHL5 by RNA-Seq." (PMID 36428630, 2022). "Finally, bladder cancers with knockdown or overexpression of UCHL5 were treated with either SC79 or LY294002 to examine the participation of the AKT/mTOR signaling pathway and the expression of downstream targets c-Myc, SLC25A19, and ICAM5." (PMID 36428630, 2022).
breast carcinoma (2 papers, 2007 to 2022). "ICAM1, ICAM4, and ICAM5 are associated with breast cancer susceptibility loci as indicators of disease severity." (PMID 35341150, 2022). "Although not completely clear from LOH, the integration of expression data also supports the role of ICAM5 as a tumor suppressor proposed by the identification of nucleotide variants that confer a risk of breast cancer." (PMID 17280605, 2007).
epilepsy (2 papers, 2012 to 2020). A brain disorder characterized by episodes of abnormally increased neuronal discharge resulting in transient episodes of sensory or motor neurological dysfunction, or psychic dysfunction. "CSF/serum IL-1β levels have been reported as a prognostic factor for epilepsy development after traumatic brain injury, and the brain-specific adhesion molecule ICAM5 can be used to discriminate between drug-responsive and drug-resistant epilepsy." (PMID 32151248, 2020).
lung carcinoma (2 papers, 2023 to 2024). "Additionally, we identified SFTPB (OR: 0.93, 95% CI 0.91–0.95), ICAM5 (OR: 0.95, 95% CI 0.93–0.97), and FLRT3 (OR: 1.10, 95% CI 1.05–1.15) as potential targets for lung cancer." (PMID 37735436, 2023).
viral infection (2 papers, 2019 to 2020). "Our study has demonstrated that there are some important differences like ICAM5 expression which may explain the clinical findings of these viral infections." (PMID 32849329, 2020).
Anxiety (1 paper, 2020). Intense feelings of nervousness, tension, or panic often arise in response to interpersonal stresses. "As reported by many research groups, Fmr1 KO mice exhibited impaired memory and exploratory and anxiety-like behaviors, which were ameliorated to some degree by lowering ICAM5 expression in DG, a pivotal area connecting amygdala and prefrontal cortex." (PMID 31882402, 2020).
behavior disorder (1 paper, 2020). "Our results indicated that ICAM5 knockdown reversed behavioral disorders in Fmr1 KO mice." (PMID 31882402, 2020). "Furthermore, ICAM5 intervention in MCs could also contribute to the reversed behavior disorder in KO mice." (PMID 31882402, 2020). "The role of ICAM5 has been well studied for the last decade; however, the therapeutic role of ICAM5 is still unclear (e.g., whether abnormal ICAM5 expression could influence any behavioral disorders in vivo is never studied)." (PMID 31882402, 2020).
diabetes (1 paper, 2026). "The reduced levels of ICAM5 in the combined cohort from baseline to 2 h post hypoglycemia may reflect impaired neuroprotection and cognitive function, consistent with hypoglycemia in those with and without diabetes." (PMID 41596469, 2026).
experimental autoimmune encephalomyelitis (1 paper, 2019). An autoimmune demyelinating disease of the central nervous system that is produced experimentally in animals by the injection of homogenized brain or spinal cord in Freund's adjuvant. "Here, we assess the role of the CNS-specific neuronal adhesion molecule ICAM-5 using experimental autoimmune encephalomyelitis (EAE), an animal model of MS." (PMID 30915022, 2019).
gastroschisis (1 paper, 2024). Gastroschisis is marked by viscera protruding, without a covering sac, from the fetal abdomen on the right lateral base of the umbilicus. "Padula investigated 75 genetic variants in 20 genes and found 11 gastroschisis-associated variants in NOS3, ADD1, GNB3, ICAM1, ICAM4, ICAM5, and NAT1 genes." (PMID 39728087, 2024).
Hypoglycemia (1 paper, 2026). A decreased concentration of glucose in the blood. "Post hypoglycemia, decreased cadherin-5 and ICAM5 were observed at 2 h and PAI-1 at 4 h, as well as increases in P-selectin at 30 min, 1 h and 24 h and ICAM3 at 24 h." (PMID 41596469, 2026). "In the combined cohort, there were significant decreases in cadherin-5 (p = 0.01) and ICAM5 (p < 0.01) at 2 h and in PAI-1 (p = 0.02) at 4 h post hypoglycemia in both T2D and controls compared to baseline." (PMID 41596469, 2026).
inflammatory bowel disease (1 paper, 2022). A spectrum of small and large bowel inflammatory diseases of unknown etiology. "Increased ICAM5 level increased risk of inflammatory bowel disease." (PMID 35772218, 2022).
injury (1 paper, 2019). Damage inflicted on the body as the direct or indirect result of an external force, with or without disruption of structural continuity. "ICAM-5 has been discussed as a marker of neuronal death in traumatic brain injury." (PMID 30915022, 2019).
ischemic stroke (1 paper, 2026). A stroke disorder caused by obstruction of blood flow to the brain, due to thrombotic (local blood clot formation) or embolic (due to a blood clot or other material traveling from another site) event. "In an in vitro ischemic stroke model, hippocampal cells were shown to express ICAM5." (PMID 41596469, 2026).
learning disabilities (1 paper, 2019). "We propose that reduced CLSTN1 or excessive ICAM5 during brain development leads to aberrations in dendritic spine formation in FXS, which may contribute to neuropathology phenotypes associated with synaptic abnormality, such as learning disabilities." (PMID 31680833, 2019).
metastatic tumors (1 paper, 2014). "Indeed, the methylation studies performed here reflect a low methylation frequency of ICAM5, a gene involved in cell-cell adhesion of which the methylation in other population was associated with aggressive, potentially metastatic tumors." (PMID 24475022, 2014).
primary progressive MS (1 paper, 2020). "As a result of disease progression, primary progressive MS (PPMS) patients with non-recoverable demyelination and neurodegeneration showed higher methylation levels for ICAM5 than RRMS patients." (PMID 31937331, 2020).
rheumatic disorder (1 paper, 2024). Inflammatory and degenerative diseases of connective tissue structures, such as arthritis. "We found that 11 proteins had a significant association with rheumatic disorders with Bonferroni correction (eTable 13 in Supplement 1), namely, interleukin-27, ICAM5, LMAN2L with JIA; TIMP4 with SSc; and 6 proteins with RA, and 4 proteins with SLE." (PMID 39729320, 2024).
infection (12 papers, 2018 to 2025). The state of being infected such as from the introduction of a foreign agent such as serum, vaccine, antigenic substance or organism. "Although ICAM-5 knockout caused a similar reduction in infection for these strains, we found that soluble ICAM-5 has a different neutralizing effect on EV-D68-947 than on EV-D68-2042 and mutant 2042-4/7." (PMID 31320648, 2019). "Soluble ICAM-5 reduced infection in cell culture when added to the medium and in vivo upon co-administration in an intracerebral (IC) neonatal mouse model of infection." (PMID 33499355, 2021). "EV-D68 replication and infection are clearly attenuated when ICAM5 is silenced or soluble ICAM-5 protein fragments are added." (PMID 31146373, 2019). "Additionally, RNA-Seq showed that PRV inoculation during the early stage of infection led to an increase in the transcription/expression of several cellular receptors [e.g., ICAM5, ICAM2, ACAN, and DSCAM] that are known to facilitate bacterial adherence." (PMID 39041808, 2024). "ICAM5 is also important for pathogen infection, auto-immune disease, and nervous system." (PMID 38601164, 2024). "The low ICAM-5 mRNA transcript expression in the human small intestinal organoids may account for the organoids’ insusceptibility to EV-D68 infection." (PMID 33477611, 2021). "Since ICAM-5 is specifically expressed on the surface of telencephalic neurons of the CNS, it is possible that ICAM-5 plays a role in infection of neuronal compartments once the virus reaches the CNS, but is not likely to be involved in dissemination of EV-D68 to the CNS." (PMID 33499355, 2021). "If cell factors, such as ICAM-5, are involved in neurovirulence, there may be functional differences in the interaction between murine and human ICAM-5 and their interactions with varying strains of EV-D68 that determine successful infection." (PMID 32784424, 2020). "Furthermore, down-regulating ICAM-5 expression in permissive cell lines inhibited EV-D68 infection in vitro, as did a soluble ICAM-5-Fc fragment (serving as a decoy receptor)." (PMID 31487952, 2019). "It was shown that the EV-D68 Fermon strain could bind to soluble ICAM-5, and knockdown of ICAM-5 decreased infection in certain human cell lines." (PMID 33499355, 2021). "Conversely, expression of ICAM-5 in non-permissive cells strongly enhanced infection by EV-D68 strains including contemporary strains." (PMID 33499355, 2021). "The intracellular adhesion molecule 5 (ICAM-5) was identified to facilitate infection by contemporary EV-D68 in otherwise non-permissive Vero cells following a sialic-acid independent mechanism." (PMID 32328043, 2020). "In this study, we confirmed the role of ICAM-5 as an EV-D68 receptor by showing that ICAM-5 knockout reduces infection by EV-D68 strains Fermon, 947, and 2042, even though this receptor was not essential for infection." (PMID 31320648, 2019).
cancer (9 papers, 2009 to 2026). A tumor composed of atypical neoplastic, often pleomorphic cells that invade other tissues. "To confirm that some of these expressions change, we selected several proteins for validation by immunoblotting including Serpinb5 (Pai3), Icam5, Thrombospondin-1 (Thbs1) whose roles are well established in cancer." (PMID 27167202, 2016). "Phenotype scanning revealed that seven out of the thirteen identified proteins (KDELC2, GSTP1, CTSS, CPNE1, ISLR2, SFTPB, and ICAM5) were associated with other traits, but none of these traits were likely to bias the associations between identified proteins and cancers." (PMID 37735436, 2023). "In conclusion, our study confirms the hypermethylation of cancer candidate genes as biomarkers and a higher methylation profile of GPNMB, ICAM5, and CHD5 genes in AA was observed." (PMID 19750230, 2009).
tumor (6 papers, 2007 to 2026). "Intercellular adhesion molecule 5 (ICAM5), a member of the immunoglobulin superfamily, regulates cell adhesion and has been implicated in tumor progression." (PMID 42258470, 2026). "Integrin and adhesion related genes including ITGA2, ITGA6, and ICAM5 were changed by −6.12, −2.75, and −5.77-fold, respectively, comparing tumor to parent cells." (PMID 33808801, 2021). "High methylation level of ICAM5 decreases the cell-to-cell adhesion in the corresponding tumor cells, increasing their invasive potential." (PMID 19750230, 2009). "At least four genes (CD109, CHD5, LGR6, and ICAM5) displayed a different level of methylation, depending on the tumor location." (PMID 19750230, 2009). "Other proteins included adhesion receptors, such as ICAM-5 and selectin, tissue-remodeling factors, such as DKK-1 and MMP-2, and metabolic enzymes, such as adiponectin and insulysin, suggesting that EMMPRIN is a multifunctional regulator of tumor development." (PMID 26416452, 2015).
neurodevelopmental disorder (2 papers, 2019 to 2024). A behavioral and cognitive disorder with onset during the developmental period that involves impaired or aberrant development of intellectual, motor, or social functions. "The specific association between the molecular mechanisms of MMP-9 and ICAM5 may reveal new avenues for individualized treatment of neurodevelopmental disorders, especially FXS, in the future." (PMID 39022311, 2024). "Future work may investigate the reason for aberrant alteration in CLSTN1 in FXS, determine the factors that regulate CLSTN1 to initiate ICAM5 transportation, and provide mechanistic insights into how dysfunctional CLSTN1 signaling pathway contributes to neurodevelopmental disorders." (PMID 31680833, 2019). "However, it remains unclear how the transport function of CLSTN1 impacts key molecule, such as ICAM5 that is known to influence dendritic spine maturation, and how CLSTN1 is involved in neurodevelopmental disorders." (PMID 31680833, 2019).
inflammation (1 paper, 2021). Aberrant reaction of the microcirculation characterized by movement of fluid and leukocytes from the blood into extravascular tissues. "Down-regulation of iCAM1 and iCAM5 genes is also an important finding, as the levels of iCAM1 were shown to be elevated in sera of PF patients, and recent studies showed that iCAM-1 inhibition reduced exacerbations of lung inflammation." (PMID 33465050, 2021).
ICAM5 also shares sentences with these, for which no sentence is quoted: Becker muscular dystrophy (1 paper); brain injury (1); Cognitive decline (1); cognitive disorder (1); depression (1); Duchenne muscular dystrophy (1); glioblastoma (1); glioma (1); immune disease (1); neurological disease (1); respiratory infections (1); rheumatoid arthritis (1); Stroke (1); systemic lupus erythematosus (1); systemic sclerosis (1); vascular insufficiency (1).